CD4 (CD4 molecule)
Diseases named in the same sentence as CD4 in open-access papers (continued):
Sharing a sentence is not in itself a finding about the gene and the disease.
HIV-1 infection (continued). "Altogether, CXCR5+CCR5− CD4 T cells that regulate humoral immunity are allowed greater freedom to operate and expand during HIV-1 infection, but at the same time can contain HIV DNA at levels at least as high as in other CD4 subsets." (PMID 28553284, 2017). "Stable release of CD4 from miR-221/miR-222 modulation in THP-1 cells, such as in the THP-1-CD4R cell line, results in efficient and productive HIV-1 infection." (PMID 29301198, 2017). "We and others found that indeed, there was a clear relative increase in Tfh compared to other CD4+ T cells in excision biopsies from both SIV and HIV-1 infections, respectively, as well as in serial fine-needle biopsies from SIV-infected macaques." (PMID 28553284, 2017). "Given that HIV-1 infection in culture is quite low (<5% GFP+ cells), cell lines and blood CD4+ T cells are advantageous because large numbers of these cells can be infected." (PMID 28241075, 2017). "This Jurkat T cell-based reporter cell line expresses CD4 and CXCR4 receptors, and enhanced GFP under the control of the HIV-1 LTR promoter, as a direct and quantitative marker of HIV-1 infection and Tat expression." (PMID 29180782, 2017). "Indeed, the antigen-specific CD4+ T cell response developing during primary HIV-1 infection includes a high percentage of CD4+ CTL, which express CCR5 and therefore may be highly susceptible to HIV-1 infection." (PMID 28289418, 2017). "CCR6 is expressed on DCs and memory CD4+ and CD8+ T cells, indicating a potentially important role for HBD2 in preventing HIV-1 infection in CCR6+ target cells through the upregulation of additional innate antiviral factors." (PMID 28839349, 2017). "IL-15 is one of the candidates as it is present at abnormally elevated levels in several diseases showing increased numbers of CD4+ CTL, including rheumatoid arthritis and HIV-1 infection." (PMID 28289418, 2017). "In HIV-1 infection, several features of HIV-specific CD4+ T cells, including proliferative capacity, surface phenotype, and secretion of multiple cytokines, are impaired in individuals with high plasma concentrations of HIV-1 RNA." (PMID 28712768, 2017). "In this respect it is interesting that Hurst showed that the expression of HLA-DR and CD38 on CD4+ and CD8+ T cells correlated with the size of total HIV-1 DNA at primary HIV-1 infection." (PMID 29375579, 2017). "This vaccine showed moderate protection against HIV-1 infection and, more interestingly, revealed that most vaccinated HIV-negative individuals presented predominantly polyfunctional effector CD4+ T cell responses against the V2 region of the envelope protein." (PMID 28289418, 2017). "An increase of Ki-67+CD4+ T cells is also seen in HIV+ subjects both in LT and in PBMC, particularly during primary HIV-1 infection." (PMID 28553284, 2017). "HIV-1 infection is blocked during reverse transcription by IFN-α pretreatment of certain cell types, including CD4+ T cells and MDMs." (PMID 27279606, 2016). "To further explore the mechanism(s) of how HIV-1 infection affects let-7i expression, we also tested the levels of primary and precursor let-7i transcripts in HIV-1-infected CD4+ T cells." (PMID 27145859, 2016). "Early HIV-1 infection is characterized by high levels of HIV-1 replication and substantial CD4 T cell depletion in the intestinal mucosa, intestinal epithelial barrier breakdown, and microbial translocation." (PMID 26762145, 2016). "Our data showed that OTX015 treatment did not cause an increase in the expression of these HIV receptors/co-receptors, suggesting that OTX015 may not pose the risk of increasing the susceptibility of CD4+ T cells to HIV-1 infection during the reactivation of HIV-1 latency." (PMID 27067814, 2016). "Although decreased CD4+ and CD8+ T-cell TREC contents have repeatedly been reported in HIV-1 infection, results from cross-sectional studies are conflicting." (PMID 27010200, 2016).
HIV-1 infection (continued). "In HIV-1 infection, IFN-γ single positive mycobacteria-specific CD4+ T cells were decreased, while the frequency of polyfunctional cells (IFN-γ+IL-2+TNF-α+) remained unchanged." (PMID 27865393, 2016). "Short-course ART during primary HIV-1 infection (PHI) (Short Pulse Anti-Retroviral Therapy at Seroconversion Trial) also delayed the outcome of a primary end point, measured as CD4+ T-cell count less than 350 cells/μL or subsequent long-term ART initiation." (PMID 27281071, 2016). "To obtain a deeper mechanistic understanding of how IFNα impacts spreading HIV-1 infection, we modeled the interaction of HIV-1 with CD4 T cells and IFNα as a dynamical system." (PMID 27010978, 2016). "Elevated blood CXCL10/IP-10 levels during primary HIV-1 infection (PHI) were described as an independent marker of rapid disease onset, more robust than peak viremia or CD4 cell nadir." (PMID 27509048, 2016). "We previously demonstrated that CD4+ T cells and macrophages from HIC are relatively resistant to HIV-1 infection." (PMID 27505169, 2016). "In comparison, HIV-1 infection of T-cells co-cultured with SLAN DC depleted CD14− CD16+ monocytes, B-cells and pDC was similar to infection of CD4+ T cells alone." (PMID 26362311, 2015). "We examined expression of CD4, CXCR4, and CCR5, receptors for HIV-1 infection, in CD14-derived osteoclasts and macrophages." (PMID 25809599, 2015). "Nucleofected CD4 T cells were then admixed with autologous CD4-depleted HLAC, infected with HIV-1NL4-3 and evaluated for HIV-1 infection by GFP expression." (PMID 26108174, 2015). "HIV-1 infection was assessed by GFP expression, p24 proteins in culture supernatants and/or HIV-1 mRNA 72 h after infection, a time point preceding CD4 T-cell depletion in HLACs19." (PMID 26108174, 2015). "It has been shown in CD4+ lymphocytes that suppression of cytoskeleton regulators (Arp2/3 and WAVE2) prevented HIV-1 infection diminishing its intracellular migration." (PMID 26379653, 2015). "The median CD4 count at baseline was 249 /μL (IQR 127–385), and 66% of the study patients were treatment-naïve for HIV-1 infection." (PMID 26535588, 2015). "Key players in HIV-1 infection, CCR5 and CXCR4 GPCRs function as co-receptors for virus entry into CD4+ target cells." (PMID 26629902, 2015). "Because CD4+ T lymphocytes are the main target of HIV-1 in vivo, Vpr’s role in HIV-1 infection and its evolutionary conservation across lentiviral species targeting a wide range of primates has remained enigmatic." (PMID 26186441, 2015). "We compared immune kinetics in individuals who were diagnosed early or late with HIV-1 infection, (thus commencing ART with different CD4+ T-cell counts), in order to investigate possible mechanisms involved in subsequent poor immune recovery." (PMID 25671649, 2015). "Surprisingly, our results with primarily effector memory LP CD4+ T cells mirrored published findings based on X4-tropic HIV-1 infection of HLAC cells, which are predominantly resting CD4+ T cells." (PMID 24495380, 2014). "HIV-1 infection in the humanized mouse model leads to persistent HIV-1 infection and immunopathogenesis, including type I interferons (IFN-I) induction, immune-activation and depletion of human leukocytes, including CD4 T cells." (PMID 25077616, 2014). "Syncytia formation is a major death pathway for CD4+ T-cell lines infected with HIV-1 and has long been considered as a marker of HIV-1 infection in these cell lines." (PMID 24714696, 2014). "We next examined the influence of HIV-1 infection on expression of CD4, CD69 and CD62L on resting CD4+ T cells." (PMID 25330112, 2014).
HIV-1 infection (continued). "Once profound CD4 lymphopenia (<200 cells/μL) has developed, mortality is similar for both HIV-2 and HIV-1 infection." (PMID 24803534, 2014). "Thus, mechanisms underlying the higher sensitivity to HIV-1 infection in M-CSF-induced macrophages are not clear at present; further studies are necessary, including comparisons of CD4 and CCR5 expression levels between M-CSF-induced and GM-CSF-induced macrophages." (PMID 24599229, 2014). "Our assay permits the simultaneous detection and quantification of HIV-1 infection in naïve, EMRA, TSCM, CM, TM, EM CD4+ T cell subsets." (PMID 24517971, 2014). "Human macrophages are one of the main targets for HIV-1 infection, despite their moderately low surface expression levels of the main HIV-1 receptor, CD4." (PMID 24465876, 2014). "Secondly, to investigate the importance of lipid rafts (as detergent resistant membranes - DRM) in HIV-1 infection, we generated genetically modified PSC-macrophages that express CD4 mutants known to be excluded from DRM." (PMID 24465876, 2014). "However, loss of cells may also be due to chronic immune activation, secondary to chronic exposure to microbial products translocated across epithelial barriers depleted of CD4 T cells during primary HIV-1 infection and alteration of homeostasis due to eventual fibrotic changes to lymphoid tissue." (PMID 25610441, 2014). "CD3+CD4+ and CD3+CD8+ T cells induced with viral epitopes are important effector cells against HIV-1 infection." (PMID 24454311, 2014). "HMBA also down regulates surface expression of CD4 in PBMC and inhibits T cell activation, preventing de novo HIV-1 infection." (PMID 24736215, 2014). "It is also likely that HIV-1 infection results in modification of antigen presentation in macrophages and dendritic cell lines, resulting in anergy of HIV-1 specific CD4+ and CD8+ T cells." (PMID 24454311, 2014). "Although previous studies have reported increased PD-1 expression in HIV-1 infection, this primarily affects virus-specific CD8+ and antigen-specific CD4+ T-cells." (PMID 24803534, 2014). "To test cell-free infection, we inoculated primary CD4+ T cells with HIV-1NL4-3 carrying the spliced GLuc reporter (HIV-1NL4-3-GLuc) and measured HIV-1 infection 36 hr post-infection." (PMID 24586176, 2014). "We found that GPR15 expression was up-regulated ex vivo on CD4+ T cells in two out of eleven HIV-1 patients, that HIV-1 infection can upregulate GPR15 in PM1 T cells and that TLR3 triggering by dsRNA up-regulated GPR15 expression on CD4+ T cells." (PMID 24558379, 2014). "Previously, we have demonstrated that pre-stimulation of resting CD4 T cells with anti-CD4/CXCR4 beads triggers cell signaling and actin reorganization that enhances HIV-1 infection of resting T cells." (PMID 23782904, 2013). "Moreover, studies also show that CD4+ T cell counts are higher and that viral rebound occurs later (and at a lower level) after the discontinuation of treatment that began during primary infection compared with treatment that began during chronic HIV-1 infection." (PMID 23803414, 2013). "In line with the correlation observed between plasma Gal-9 levels and viral load, intracellular levels of Gal-9 in CD4+ T cells, CD8+ T cells, NK cells, monocytes, and mDCs all positively correlated with viral load in subjects with HIV-1 infection." (PMID 23866914, 2013). "Overexpression of gelsolin-EGFP did not affect the cellular distribution or the cell-surface expression of CD4, CXCR4 or CCR5, the receptors required for HIV-1 infection (respectively)." (PMID 23575248, 2013). "These cells express the receptor CD4 and the coreceptors CXCR4 or CCR5 required for HIV-1 infection." (PMID 24009706, 2013). "Antiretroviral therapy (ART) has significantly modified the natural course of HIV-1 infection, resulting in decreased HIV-1 plasmaviremia, increased CD4 lymphocytes, and decreased opportunistic infections, indicating a restoration of immune functions." (PMID 24151490, 2013).
HIV-1 infection (continued). "Our finding that MVs within the viral inocula restrict HIV-1 infection of DCs may reflect a further mechanism by which DCs are able to control viral infection, or more importantly, their induction of partial maturation may facilitate viral transfer to CD4+ lymphocytes." (PMID 24204260, 2013). "It was reported that in primary HIV-1 infection, controllers had an early expansion of both classical HTL, and cytolytic CD4 T cells which were able to kill infected cells directly." (PMID 23459797, 2013). "The modified CD4+ T cells proliferated normally and showed resistance to CXCR4 tropic HIV-1 infection in vitro." (PMID 24284874, 2013). "However, a small proportion of EC developed declining number of CD4+ T cells despite undetectable levels of HIV-1 viremia as HIV-1 patients with progressive disease, that was associated to reduced thymic output mirrored by thymic dysfunction during untreated progressive HIV-1 infection." (PMID 23577012, 2013). "HIV-1 infection was also impaired in other humanized immunodeficient mouse line, the NOD-RAG2−/-γc−/−strain, when these mice were engrafted with CD4+ T cells or CD34+ HSCs transduced with huTRIM5Cyp." (PMID 24167505, 2013). "The predominant evidence suggests that LTNP and EC have effective CD4 and CD8 T-cell activities that in these rare cases are able to target critical epitopes in HIV-1 Gag and severely limit HIV-1 infection and replication." (PMID 23630526, 2013). "For some of the common immunological features of HIV-1 infection and CVID, most notably the low CD4 T cell counts and CD8 T cell activation, partial normalization was observed in the CVID patients after immune reconstitution treatment with IVIg." (PMID 24130688, 2013). "Based on these observations, and on the fact that CD4+ T cells from chimpanzees and humans are equally susceptible to HIV-1 infection in vitro, we sought to determine whether a Siglec-mediated cell-intrinsic mechanism contributes to differences in outcomes of HIV-1 infection in CD4+ T cells." (PMID 22945238, 2013). "Our findings are in agreement with previous studies that reported that VPAC1 facilitates productive HIV-1 infection in CD4+ tumor cell lines, and that VPAC2 activation inhibits HIV-1 integration and viral production in CD4+ tumor cell lines and PBMCs." (PMID 23818986, 2013). "Rag2−/−γc−/− animals lack B, T, and NK cells, can be engrafted with either CD4+ T cells or CD34+ HSC, and in both cases, support HIV-1 infection." (PMID 24086129, 2013). "To examine the role of Vpr in HIV-1 infection, we compared the infection of the two viruses on PHA-activated PBMCs, primary CD4+ T-cells, and MDDCs." (PMID 22570689, 2012). "Since we observed a distinct deficit in Vpr− single-cycle HIV-1 infection in the HuT/CCR5 cell line, which was similar to what was observed in CD4+ primary T-cells, we performed quantitative PCR analysis in infected HuT/CCR5 cells and MDDCs." (PMID 22570689, 2012). "We found that HIV-1 infection results in altered phenotype and function of MTB-specific CD4+ T cells at the site of disease towards a less differentiated and more polyfunctional phenotype." (PMID 22215422, 2012). "Similar to what was observed with CD4+ primary T-cells, the infection of HuT/CCR5 cells with Vpr+ HIV-1 was 15-fold higher (P<0.05) compared with Vpr− HIV-1 infection." (PMID 22570689, 2012). "GHOST/R5 cells are human osteosarcoma cells that express CD4 and CCR5 and contain a GFP gene under the control of the HIV-2 LTR promoter, which is expressed during HIV-1 infection via Tat transactivation acting as an indicator of infection." (PMID 22570689, 2012). "The expression levels of CD69, an early marker of CD4+ T cell activation, in WT HIV-1 infected cells were increased compared to mock-infected control cells at 3 dpi, indicating that HIV-1 infection activates resting CD4+ T cells." (PMID 22479639, 2012).
HIV-1 infection (continued). "During HIV-1 infection, viruses were proposed to selectively downregulate or even deplete the pool of CD40L-expressing CD4+ T cells." (PMID 22606007, 2012). "In the absence of combination antiretroviral therapy (cART), HIV-1 infection is maintained in a chronic state- characterized by high levels of viral production with associated immune activation that is responsible in large part for progressive CD4+ T cell depletion." (PMID 22319447, 2012). "Together, our results suggest that replication-competent HIV-1 infection of DCs can down-regulate DC-SIGN and CD4 expression and facilitate DC maturation in a largely Nef-independent manner." (PMID 22479639, 2012). "For example, it was recently demonstrated that a decline in the quality of HIV-1-specific CD4+ and CD8+ T cells in HIV-1 infection, including functional cytokine production, and a shift toward a memory cell phenotype, occurred over a 7 year period." (PMID 23346088, 2012). "T-cell exhaustion is observed during HIV-1 infection; and previous reports have shown higher levels of CTLA-4 or PD-1 (protein or mRNA) on circulating CD4+ and CD8+ T-cells from HIV-1 infected patients, compared to uninfected individuals." (PMID 22276176, 2012). "For resting CD4 T cells, in which the cytoskeletal actin is relatively static, the Jas IC50 dosage for HIV-1 infection was 60 nM, whereas for transformed Rev-CEM indicator cells, the Jas IC50 for HIV-1 infection was 250–500 nM." (PMID 22640593, 2012). "Since CD4+ T cells are the primary targets for HIV-1 infection/replication in vivo, the goal of this study was to evaluate cocaine-induced enhancement of HIV-1 replication in primary CD4+ T cells." (PMID 23251514, 2012). "The HIV-1 host receptors CD4, CCR5 and CXCR4 are involved in the early steps of HIV-1 infection and thus represent valuable targets for the identification of antiviral peptides or neutralizing Abs." (PMID 22606007, 2012). "Although SAMHD1 imposes an important block to HIV-1 infection, disruption of this block cannot restore HIV-1 replication in resting CD4+ T cells, indicating that there are additional blocks in these cells." (PMID 23254112, 2012). "However, in CD4+ T cells we could detect IRF3 phosphorylation after 48 hr of HIV-1 infection." (PMID 23159053, 2012). "A variety of cell lines have been made which stably express CD4, CCR5, or both coreceptors on the cell surface to evaluate coreceptor inhibitors of HIV-1 infection." (PMID 22848825, 2012). "In sum, current data indicates that myeloid cells play an important role in the pathogenesis of HIV-1 infection as a relatively long-lived target of HIV and as a viral conduit to CD4+ T cells." (PMID 23344558, 2012). "Many HIV cohorts demonstrated factors potentially affect the recovery of CD4 T- lymphocyte including age, HCV serology, duration of HIV-1 infection, CDC stage, baseline HIV-1 RNA levels, baseline CD4 count, and adherence of cART." (PMID 22060823, 2011). "It has been reported that A3G in resting CD4+ cells and monocytes are predominantly in its low-molecular-mass (LMM) active form making these cells refractory to HIV-1 infection." (PMID 22152111, 2011). "PHA-activated CD4+ T cells were used as a positive control, which displayed around 30% cells expressed CD69 expression and supported efficient HIV-1 infection in treated T cells." (PMID 22110688, 2011). "Profound loss of Th17 cells and reduction of CD161 CD4 cells, which may limit Th17 reconstitution in untreated HIV-1 infection, is associated with a gradual decline in Tregs, increased immune activation, and disease progression in blood product associated HIV-1 infection in hemophilia patients." (PMID 22292110, 2011). "Exposure of monocytes to S-CM blocked up-regulation of CD4 and CCR5 expression during monocyte differentiation into macrophages and inhibited productive HIV-1 infection in differentiated macrophages." (PMID 21637819, 2011).